IL13 (interleukin 13)
Diseases named in the same sentence as IL13 in open-access papers (continued):
Sharing a sentence is not in itself a finding about the gene and the disease.
asthma (continued). "It is biologically plausible that the IL-13 +1923C/T polymorphism which can affect IgE level could influence the susceptibility to asthma." (PMID 23841068, 2013). "In addition, a significant association between IL13+2044A/G polymorphism and asthma risk was observed (OR = 1.18, 95% CI 1.08–1.28, P = 0.0002)." (PMID 23437086, 2013). "IL13 is located on chromosome 5q31, and has been consistently associated with asthma." (PMID 24314122, 2013). "Importantly, reduction in IL-13 levels using IL-13 deficient mice or IL-13 neutralization strategies have confirmed an essential role for this cytokine in driving major correlates of asthma pathology, including AHR, pulmonary eosinophilia, and mucus secretion." (PMID 23936192, 2013). "Previous studies have shown that household environmental tobacco smoke (ETS) and IL-13 genetic variants may have interactive effects on asthma phenotypes." (PMID 23382814, 2013). "Association of IL-13 haplotypes with asthma phenotypes among children." (PMID 23382814, 2013). "In our data, IL-13 genetic variants showed significant adverse effects on asthma phenotypes." (PMID 23382814, 2013). "This suggests that the mutant T-allele at position −1111C>T of the human IL-13 gene promoter may have an effect on the development of asthma in Malaysian asthmatics." (PMID 23865080, 2013). "In addition, there was a combined effect of IL-13 gene polymorphisms and tobacco smoke on persistent childhood wheezing and asthma." (PMID 23841068, 2013). "It is also possible that different polymorphisms within the IL-13 gene may contribute to the development of asthma in different populations." (PMID 23865080, 2013). "Hence, we performed a meta-analysis of all eligible studies to derive more precise estimation of the associations of IL-13 −1112C/T and +2044A/G polymorphisms with asthma risks." (PMID 23437086, 2013). "Determination of the genetic effects of IL-13 polymorphisms on asthma and subgroup analyses." (PMID 23437086, 2013). "Previous studies have shown that promoter variant in IL-13 (SNP rs1800925) could enhance IL-13 transcription and was associated with atopy, asthma and increased bronchial hyper-reactivity." (PMID 23382814, 2013). "Two single nucleotide polymorphisms (SNPs) of IL-13 have been investigated in relation to asthma." (PMID 23841068, 2013). "Thus, our results should be interpreted with caution and more studies are still needed to evaluate the effect of IL-13 −1112C/T polymorphism on asthma risk." (PMID 23437086, 2013). "The increased amounts of IL-4 and IL-13 present in γc deficient mice could amplify signaling through the Type II R and enhance asthma responses." (PMID 23940740, 2013). "In addition, Corren and colleagues demonstrated that lebrikizumab (a monoclonal antibody to IL-13) treatment was associated with improved lung function in patients with asthma." (PMID 23841068, 2013). "Asthma susceptibility genes are mapped to a region on human chromosome 5q31-q33, which contains a cluster of proinflammatory cytokine genes such as interleukin-13 (IL-13), which is associated with asthma." (PMID 23865080, 2013). "These augmented asthma phenotypes were associated with enhanced production of IL-13." (PMID 23452625, 2013). "In conclusion, this meta-analysis suggested that IL-13 −1112C/T and +2044A/G polymorphisms may be associated with the risk of asthma." (PMID 23437086, 2013). "The relationship between the presence of functionally relevant polymorphisms in the IL-13 gene and IL-13 production is of clinical interest because of the regulatory role of IL-13 in the pathogenesis of asthma along with interindividual differences in IL-13 production capacity." (PMID 23865080, 2013). "Based on the haplotype analyses in the present study, we found that three variants of 4 SNPs in IL-13 gene might significantly affect risks of asthma phenotypes in children." (PMID 23382814, 2013).
asthma (continued). "Therefore, we performed this meta-analysis to assess the association between IL-13 +1923C/T polymorphism and asthma risk." (PMID 23841068, 2013). "Therefore, we performed a meta-analysis to assess the associations between IL-13 polymorphisms and asthma susceptibility." (PMID 23437086, 2013). "Airway inflammation associated with Th2 cytokines such as IL-4 and IL-13 is a principal feature of asthma, but whether these cytokines elicit expression of HLA-G is not known." (PMID 23327606, 2013). "IL-13 can in turn promote susceptibility to chlamydial lung infection that could in theory produce a positive feedback loop to create or worsen asthma." (PMID 22545149, 2012). "Gene profiling data of the current study revealed (i) a significant increase of IL13 mRNA levels in NP tissues, (ii) significant associations with the clinical parameters such as atopy and asthma, and (iii) a strong positive correlation between expression levels of IL13 and IL5." (PMID 21984922, 2011). "IL-13 is a potent effector cytokine for asthma, as it can directly cause airway hyperreactivity, mucus over-production, increased pulmonary vessel permeability, and smooth muscle hypertrophy, effects that have been shown to contribute to pulmonary dysfunction and respiratory distress." (PMID 22054060, 2011). "With respect to the IL13 gene, two single nucleotide polymorphisms (SNPs) including C-1055T (rs1800925) in the promoter region and Arg130Gln (rs20541) in the exon 4 were reported to be associated with asthma." (PMID 22087298, 2011). "Th2 cells and their signature cytokines IL-4, IL-5, and IL-13 have key pathogenic roles in asthma." (PMID 21772663, 2011). "In the conventional rodent asthma model, recruited eosinophils are associated with airway remodelling including peribronchial fibrosis, smooth muscle hyperplasia, and mucus secretion with the involvement of eotaxin and IL-13." (PMID 21896169, 2011). "Potential explanations for enhanced IL-13+ T cell accumulation selectively in female asthmatics is an interaction between high levels of female sex hormones and the asthma/atopic environment or asthma/atopy susceptibility genetic polymorphisms." (PMID 20667106, 2010). "In addition, the ACE D/I, FcεRIβ -6843G/A, TNF-α -308G/A, IL-13 -1923C/T and IL-13 -2044A/G polymorphisms were associated with asthma risk in Chinese adults." (PMID 20868478, 2010). "ADAM33, FcεRIβ, RANTES, TNF-α, ACE, β2-AR, IL-4R and IL-13 genes could be proposed as asthma susceptible genes in Chinese population." (PMID 20868478, 2010). "This association between IL-13 and asthma in humans is supported by animal models." (PMID 19602238, 2009). "The data demonstrate a useful approach to assay for transplacental passage of functional maternal molecules, and indicate that molecules other than IL-4 and IL-13 may mediate transplacental effects in maternal transmission of asthma risk." (PMID 19252738, 2009). "NIEHS has funded research on genes associated with asthma susceptibility and has focused funding of genetic research on interleukin-4 and interleukin-13, two cytokines that, among other things, help regulate adaptive immunity to allergens and other asthma triggers." (PMID 19654926, 2009). "The Th2 cytokine interleukin (IL)-13 has been implicated in the pathogenesis of asthma." (PMID 19602238, 2009). "CD38 has a role in airway hyperresponsiveness, a hallmark of asthma, since deficient mice develop attenuated airway hyperresponsiveness compared to wild-type mice following intranasal challenges with cytokines such as IL-13 and TNF-α." (PMID 18341691, 2008). "In the current study we observed that children who had the common genotype for IL13 polymorphisms (haplotype pairs or SNP rs20541) have increased risk of early onset persistent wheeze and persistent childhood asthma in relation to maternal smoking during pregnancy." (PMID 18186920, 2008).
asthma (continued). "Indeed several IL-13 polymorphisms were identified which are associated with increased levels of IgE, a predictor of asthma phenotype." (PMID 18949100, 2008). "Moreover, asthma is associated with the occurrence of atopic dermatitis, chronic sinusitis, allergic rhinitis, and a high profile of T2-type cytokines, such as IL-4, IL-5 and IL-13." (PMID 40723867, 2025). "IFN-γ inhibits ILC2 proliferation and IL-13 expression in vivo and in vitro, thereby alleviating RV-induced mucous metaplasia, and its deficiency in the production in immature mice may lead to the development of asthma-like phenotypes after early RV infection." (PMID 40636260, 2025). "Conversely, eosinophilic asthma, classified as type-2 high asthma, is commonly associated with allergic triggers and is characterized by a significant presence of eosinophils within the airways, and associated with elevated levels of cytokines, like IL-4, IL-5, IL-13, and IgE." (PMID 40512736, 2025). "High IgE levels may also be associated to T2 high asthma, and like FeNO the T2 high-associated increased total IgE levels decreased during inhibition of alarmin IL-33, IL-13 and dual IL-4 and IL-13 signalling." (PMID 40980110, 2023). "In comparison with placebo, anti-IL-13/-4 agents were associated with a decrease in exacerbations that needed hospitalization or emergency department visit, in spite of increased adverse events, whereas no significant improvements in health-related quality of life and asthma control were observed." (PMID 36483465, 2022). "For example, it is thought an inflammatory type 2 response associated with cytokines (IL-4, IL-5, and IL-13) and the clinical inflammatory phenotype of asthma marked by eosinophilia may have protective effects through the activation of the antiviral host defence and promotion of viral clearance." (PMID 36105903, 2022). "Additionally, IL13 rs1295686*G, which has frequencies of 0.225, 0.375 and 0.796 among the Zimbabwean sample, Africans and Europeans, respectively, has been associated with decreased risk of asthma and reduced IgE expression." (PMID 35759449, 2022). "In addition to regulating IgE production, IL-13 and IL-4 are implicated in cardinal features of asthma, such as extravasation and trafficking of eosinophils into the tissue, goblet cell maturation, mucus secretion, bronchial hyperresponsiveness, and tissue remodeling." (PMID 33643321, 2021). "Indeed, IL-13, an inflammatory cytokine highly associated with asthma induced activation of STAT6 has been shown to increase mucin expression and mucus metaplasia in both airway epithelial cells and submucosal glands in mice and has been linked to goblet cell hyper/metaplasia in humans." (PMID 35386986, 2021). "Type 2 inflammation (type 2 T helper cell lymphocyte) is common in asthma patients, and it is linked to certain inflammatory cells (mast cells, eosinophils, type 2 T helper cell lymphocyte, IgE-producing plasma cells, and basophils) and cytokine profiles (IL-13, IL-5, IL-4)." (PMID 34516405, 2021). "However, in asthmatic individuals, RV infections have been shown to induce increased levels of interleukin (IL)-4 and IL-13, along with an increased infiltration of macrophages and neutrophils on the respiratory tract, which is linked to the ability of RV to enhance asthma exacerbations." (PMID 34571943, 2021). "IL-13 might be implicated as a mediator of tight junction disruption in asthma." (PMID 34366865, 2021). "The Th2 cytokine, interleukin-13 (IL-13), is regarded as a key effector molecule for goblet cell metaplasia, reduction of cilia beat frequency, eosinophil infiltration, IgE production, mucus hypersecretion, and bronchial hyper reactivity associated with asthma." (PMID 33572760, 2021).
asthma (continued). "The best known phenotype of asthma is allergic asthma, in which these symptoms are caused by inhaled allergens such as house dust mites, animal dander, fungi, and pollens, triggering an immunological response driven by T helper type 2 (Th2) cells and their associated cytokines IL-4, IL-5, and IL-13." (PMID 32194407, 2020). "On the other hand, the reQTL for IL13 in neonatal PHA-stimulated T cells appeared to share causal variants with allergic disease and asthma, suggesting that this reQTL may affect allergic disease risk via mechanisms that do involve T cell activation and interleukin 13 (IL-13)." (PMID 32724101, 2020). "Thus, asthma has generally been associated with type 2 airway inflammation characterized by elevated levels of immunoglobulin E, eosinophils, and several interleukins (IL), such as IL-4, IL-5, IL-13, and IL-9." (PMID 29977241, 2018). "Importantly, IL-13 responses are associated with allergen associated airway disease such as asthma." (PMID 29357863, 2018). "Furthermore, interrogating how other cytokine combinations that are frequently associated with the asthma phenotype (e.g. IL-13, IL-4, TSLP) may reveal novel mechanisms for regulating XDH expression and uric acid production." (PMID 28863172, 2017). "A respiratory allergy such as asthma is predominantly caused by Th2 inflammatory responses in the airway, which are characterized by the induction of Th2 cytokines including IL-4, IL-5, and IL-13 that lead to IgE production, increased mucus production, and eosinophilia." (PMID 28824649, 2017). "In addition, anti-interleukin-9 and anti-interleukin-13 decreased symptoms associated with asthma." (PMID 26101464, 2015). "While IL-13 is closely associated with allergic asthma and adaptive immunity, it is also valuable to know how it may affect molecules and pathways of innate immunity in asthma." (PMID 25848896, 2015). "IL-13-mediated induction of AMCase by airway epithelial cells and macrophages may underlie the development of airway hyper-responsiveness and inflammatory cell infiltrate in asthma." (PMID 26528713, 2015). "However, mixed success with regard to anti-IL-4 and anti-IL-13 interventions in clinical trials to date confirms the need for a better understanding of the mechanisms of pathogenesis underlying the different Th2 ‘endotypes’ seen in asthma." (PMID 26362930, 2015). "However, there is no related literature concerning the association between childhood exposure to household carpet use and IL-13 genetic polymorphisms that might be involved in asthma susceptibility." (PMID 23382814, 2013). "The cytokines IL-4 and IL-13 are abundantly present in the lungs of asthmatics, and it may therefore not come as a surprise that markers expressed by M2 macrophages have been associated with asthma." (PMID 23533311, 2013). "We believe that IL-13 genetic variants and exposure to household carpet use may synergistically induce high IL-13 levels to inflammation, which would result in the occurrence of asthma phenotypes in children." (PMID 23382814, 2013). "Additionally, sputum IL-13 concentration is negatively associated with asthma control." (PMID 23283176, 2011). "We found that both IL-13 and IL-13R130Q stimulate the same set of important genes that encode for proteins which may be clinically relevant for regulating airway hyper-responsiveness, airway inflammation and airway remodeling, key characteristics of asthma." (PMID 15661077, 2005). "In patients with asthma who have a pre-existing tendency toward allergic (Th2-skewed) inflammation, the presence of Th2 cytokines—particularly IL-4 and IL-13—amplifies the release of TSLP and IL-8 from small airway epithelial cells." (PMID 41576028, 2026). "Type 2 inflammation contributes to the pathogenesis of asthma through the production of cytokines IL‐4, IL‐5, and IL‐13, thereby inducing characteristic features of asthma such as elevated eosinophil levels and airway hyperresponsiveness." (PMID 41568067, 2026).
asthma (continued). "In contrast, adult T2-high asthma remains dominated by Th2 cytokines (IL-4, IL-5, and IL-13) and eosinophilia, showing robust response to biologics and corticosteroids." (PMID 41601686, 2026). "Dupilumab attenuated the expression of both TSLP and IL-8 induced by co-stimulation with dsRNA and IL-4/IL-13 in HSAECs, suggesting its potential therapeutic benefit in virus-induced asthma exacerbations, particularly in type 2 asthma." (PMID 41576028, 2026). "T2-high asthma is characterized by upregulated type 2 immune pathways, specifically involving IL-4 and IL-13 gene expression." (PMID 41601686, 2026). "In OVA‐induced asthma models, studies have demonstrated that ILC2s contribute to the production of IL‐5 and IL‐13 in the lungs, comparable to Th2 cells, thereby inducing allergic airway inflammation." (PMID 41568067, 2026). "Recent studies have shown that the control of IgE class switching in asthma is closely associated with TFH cells producing IL‐4 and IL‐13." (PMID 41568067, 2026). "This pattern is consistent with the emerging view that pediatric non-T2 asthma often reflects a Th1/Th17-skewed, neutrophil-predominant endotype, in contrast to the classic Th2/IL-4/IL-5/IL-13-driven phenotype that dominates many adult cohorts." (PMID 41601686, 2026). "Asthma is mainly driven by type 2 inflammation, with IL-4, IL-5, and IL-13 inducing eosinophilia, IgE production, mucus hypersecretion, and airway remodeling." (PMID 42193381, 2026). "In contrast to the innate immunity mediated by ILC2s, Th2 cells modulate adaptive immunity that secretes copious amounts of IL‐4, IL‐5, and IL‐13 in an antigen‐dependent manner, thereby playing a pivotal role in Type 2 inflammation in asthma." (PMID 41568067, 2026). "Specifically, upon stimulation, these cells secrete Type 2 cytokines (IL‐4, IL‐5, IL‐9, and IL‐13) which promote Type 2 inflammatory response in the body and lead to characteristic symptoms of asthma and airway remodeling." (PMID 41568067, 2026). "The Th2 inflammatory pathway is frequently upregulated during these infections, associated with increased production of cytokines such as IL-4, IL-5, and IL-13, which aggravate asthma symptoms." (PMID 41738365, 2026). "During rhinovirus infection, type 2 cytokines—including IL-4 and IL-13—were significantly elevated in both nasal and bronchial samples of asthma patients." (PMID 41576028, 2026). "The proliferative capacity of ILC2 and the secretion of IL‐5 and IL‐13 are enhanced in individuals with severe asthma." (PMID 41568067, 2026). "Dupilumab, which attenuates Th2-driven inflammation through inhibition of both IL-4 and IL-13 signaling, has demonstrated efficacy in a wide range of allergic conditions, including asthma and AD." (PMID 40004611, 2025). "T2-high asthma is defined by eosinophilic inflammation and elevated levels of T helper 2 (Th2) cytokines, mainly IL-4, IL-5, and IL-13." (PMID 40355861, 2025). "This strategy is particularly promising for T2-high asthma, a subtype driven by heightened sensitivity to Th2 cytokines like IL-4 and IL-13." (PMID 40806756, 2025). "For instance, bispecific monoclonal antibodies like IBI 3002 (targeting IL-4Rα and TSLP) and lunsekimig (targeting TSLP and IL-13) aim to address both T2 and non-T2 inflammation in asthma." (PMID 40004611, 2025). "Th2-high asthma, one of the most well-characterized endotypes, is driven by IL-4, IL-5, and IL-13-mediated eosinophilic inflammation, airway remodeling, and epithelial dysfunction." (PMID 40503233, 2025). "The level of IL‐13 in bronchial lavage fluid in asthma was increased in females compared with males (p = 0.0007)." (PMID 40022441, 2025). "In asthma trials, dupilumab treatment led to significant reductions in FeNO, reflecting IL-13 blockade in the airway epithelium and lowered circulating inflammatory markers." (PMID 40843371, 2025).